NTN1 (netrin 1)
Diseases named in the same sentence as NTN1 in open-access papers (continued):
Sharing a sentence is not in itself a finding about the gene and the disease.
glioblastoma (16 papers, 2011 to 2025). The most malignant astrocytic tumor (WHO grade IV). "In tumors associated with the CNS, such as retinoblastoma and glioblastoma, netrin-1 did promote neovascularization." (PMID 38375479, 2024). "Netrin-1 promotes the invasion and angiogenesis of glioblastoma cells by activating RhoA, cathepsin B, and cAMP response element binding protein or the Notch pathway." (PMID 32251318, 2020). "Based on the results that netrin-1 induces glioblastoma cell invasion, we tested the netrin-1 effect on medulloblastoma." (PMID 30532711, 2018). "Consistent with the results of glioblastoma cells, netrin-1 induces EC stress fiber formation and invasion via a RhoA and cofilin pathway." (PMID 30532711, 2018). "Mechanistically, netrin-1 induces glioblastoma cell stress fiber formation by activating the RhoA and cofilin pathway." (PMID 30532711, 2018). "Taken together, netrin-1 activates glioblastoma cell invasion in a RhoA-, CREB-, and CatB-dependent manner." (PMID 30532711, 2018). "Netrin-1 promotes glioblastoma cell migration and invasion by Transwell coated with gelatin (migration) or Matrigel (invasion) assays." (PMID 30532711, 2018). "In in vivo xenograft models, glioblastoma cells overexpressing netrin-1, display metastatic lesions in lymph nodes after 1-month post-resection of primary tumors implanted subcutaneously on the dorsal flank of nude mice." (PMID 30532711, 2018). "In glioblastoma tumor biopsies netrin-1 localized to hypoxic tumor areas known to be rich in the stem-like cells." (PMID 28069038, 2017). "We concluded based on our results and previous studies that netrin-1 is essential for glioma proliferation not only in glioblastoma stem cells, but also in glioma cells, and is also critical in multiple stages of glioma tumorigenesis." (PMID 28710382, 2017). "This study demonstrates that NTN1 is an important regulator of stemness and motility of glioblastoma cells." (PMID 28069038, 2017). "Intracranial mouse xenograft models were utilized to investigate the effects of netrin-1 on glioblastoma growth and invasion in vivo." (PMID 28069038, 2017). "In xenograft mouse models netrin-1 expression altered the phenotype of non-invasive glioblastoma cells into diffusively invading and increased the expression of glioma stem-like cell markers." (PMID 28069038, 2017). "Another recent study also discovered that netrin-1 knockdown inhibited glioblastoma stem-like cells proliferation, invasion and angiogenesis." (PMID 28710382, 2017). "Netrin-1 activates Notch signaling in glioblastoma cells resulting in subsequent gain of stemness and enhanced invasiveness of these cells." (PMID 28069038, 2017). "Our findings describe netrin-1 as an important regulator of glioblastoma cell stemness and motility." (PMID 28069038, 2017). "Reduced expression of netrin-1 has been documented in brain tumors, including glioblastoma, however, a role for netrins regulating brain tumor cell migration has not been established." (PMID 21980448, 2011). "Glioblastoma is one of the most common tumors in neurosurgery, and evidence in recent years suggests that Netrin-1, as an atypical angiogenic ligand, may be involved in the promotion of neovascularization in glioblastoma." (PMID 35493300, 2022). "Netrin-1 promotes glioblastoma and medulloblastoma cell invasion in a RhoA-dependent manner." (PMID 30532711, 2018). "Furthermore, a distinct invasion pattern where netrin-1 positive cells were following the invasive stem-like cells was detected both in mouse models and ex vivo human glioblastoma tissue cultures." (PMID 28069038, 2017). "The localization of netrin-1 was analyzed utilizing fresh frozen glioblastoma tissues." (PMID 28069038, 2017). "Shimizu and colleagues have shown that netrin-1 could activate RhoA and cathepsin B to promote glioblastoma cell migration and angiogenesis." (PMID 28710382, 2017).
glioblastoma (continued). "Furthermore, it deciphers a novel mechanism where NTN1 activates Notch signaling and subsequent stemness in invasive glioblastoma cells." (PMID 28069038, 2017). "Therefore, we have here investigated the effects of netrin-1 on glioblastoma pathogenesis and glioblastoma cell stemness." (PMID 28069038, 2017). "The glioblastoma-derived cell lines tested express either netrin-1 (U343, U373) or netrin-3 (U87)." (PMID 21980448, 2011). "Overexpression of netrin-1 could activate Notch signaling to mediate glioblastoma cell invasion." (PMID 28710382, 2017). "Elevated netrin-1 expression in gliomas, ranging from 2.16- to 4.545-fold, was reported in 7 of the datasets including anaplastic astrocytoma (n = 42), anaplastic oligoastrocytoma (n = 39), oligodendroglioma (n = 73), diffuse astrocytoma (n = 30) and glioblastoma (n = 188)." (PMID 28710382, 2017). "Importantly, the combined action of netrin-1 and laminin-1 may influence glioblastoma cell migration in vivo." (PMID 21980448, 2011). "GSEA analysis revealed pathways such as citric acid cycle, ion channel transport, Netrin-1 signaling, trafficking of AMPA receptors, and ion homeostasis to be enriched in the fluorescing regions of glioblastomas." (PMID 37358939, 2023). "Netrin-1 induces phosphorylation of the ERK and CREB (cAMP-response element-binding protein) in glioblastoma cells." (PMID 30532711, 2018). "We determined that the human glioblastoma cell lines U87, U343, and U373 all express neogenin, UNC5 homologues, and netrin-1 or netrin-3, but only U87 cells express DCC." (PMID 21980448, 2011). "Using human glioblastoma cell lines, we provide evidence that DCC is required for chemoattraction to netrin-1 and slows the rate of spontaneous cell migration." (PMID 21980448, 2011). "Netrin-1 upregulation upon chemotherapeutic drugs treatment is not tumour type specific as netrin-1 upregulation was seen in at least one cell line of breast, lung, colon, pancreatic and ovarian cancers, as well as in neuroblastoma and glioblastoma cell lines." (PMID 24293316, 2013).
neuroblastoma (16 papers, 2011 to 2024). Neuroblastoma (NB) is the most common solid, extracranial childhood tumor. "Netrin-1 isoform associated with a poor prognosis has been detected in neuroblastoma, bronchioalveolar carcinoma, breast and colon cancer." (PMID 34361013, 2021). "For example, Netrin-1 activates Integrin β1 to drive migration and metastasis of neuroblastoma and, of particular note, both proteins are in a complex together." (PMID 39172021, 2024). "The upregulation of netrin-1 can be observed in many types of cancers, such as gastric cancer, ovarian cancer, and neuroblastoma, and it promotes their progression." (PMID 37038247, 2023). "DeGeer and colleagues reported that tyrosine phosphorylation of Trio regulates netrin-1/DCC-mediated cortical axon outgrowth in N1E–115 neuroblastoma cells." (PMID 37528624, 2023). "UNC-5 has been shown to induce neurite outgrowth in neuroblastoma cells in a netrin-1-dependent manner and to modulate synaptic differentiation in motor neuron dendrites in C. elegans." (PMID 26058786, 2015). "As recently described a truncated ΔN-netrin-1 isoform regulating tumor cell proliferation of neuroblastoma cells is localized to the nucleus and nucleolus." (PMID 24647424, 2014). "NTN1 up-regulation was suggested as a potential marker for poor prognosis in infants diagnosed with stage 4S neuroblastoma." (PMID 21789787, 2011). "The neuroblastoma cell line SH-SY5Y and the human normal keratinocyte cell line HEKn were used, respectively, as high and poor cellular expression controls for Netrin-1." (PMID 36361539, 2022). "It was proposed that interference with the NTN1 autocrine loop in malignant neuroblasts may represent an alternative therapeutic strategy, as it was shown that disruption of this loop triggers cell death and inhibits metastasis of neuroblastoma in avian and mouse models." (PMID 21789787, 2011). "Moreover, Neogenin-1, which was detected in all tumor stages and was required for neuroblastoma cell migration, was found in a complex with integrin β1, FAK, and Netrin-1." (PMID 33724150, 2021). "Recent results obtained in our laboratory indicate that interaction between Netrin-1 and NEO1 triggers the activation of Integrin β1 (ITGB1) through the key integrin signaling component Focal Adhesion Kinase (FAK), which promotes cell migration and, consequently, metastasis in neuroblastoma." (PMID 34361013, 2021). "Public databases contain extensive information regarding the expression of NEO1 and its ligands Netrin-1 (NTN1) and Netrin-4 (NTN4) in primary neuroblastoma (NB) tumors." (PMID 28038459, 2017).
Alzheimer disease (14 papers, 2013 to 2025). A progressive, neurodegenerative disease characterized by loss of function and death of nerve cells in several areas of the brain leading to loss of cognitive function such as memory and language. "In addition, the involvement of NF-κB-NLRP3 inflammasome pathway inhibition by NTN-1 might lead to a new agent for the underlying pathophysiology that is responsible for antagonizing and alleviating Alzheimer's disease." (PMID 40357234, 2025). "Interestingly, studies have shown that Alzheimer’s disease, a neurodegenerative process characterized by accumulation of amyloid beta in brain tissue, which results in functional/cognitive decline, is associated with poor Netrin-1 expression." (PMID 36361539, 2022). "We recently find that the Netrin-1 expression is significantly increased in the brain tissue of patients with Alzheimer’s disease (AD), and highly correlated with Aβ in their levels." (PMID 38638604, 2024). "Netrin-1 has been studied in Parkinson’s Disease (PD), Alzheimer’s disease (AD) and other types of neurological disorders, and we have found new evidence of Netrin-1 involved in AD pathogenesis." (PMID 38638604, 2024). "In Alzheimer’s disease (AD) rats, it has been demonstrated that NTN-1 concentrations in serum were positively correlated with the systemic expression of IL-10." (PMID 35095412, 2021). "Upregulation of genes included those involved with apoptosis (Ntn1, Adora1, and Ache) and Alzheimer’s disease (ApoE, Apbb1)." (PMID 24019935, 2013). "Interestingly, decreased NTN‐1 levels correlate with cognitive decline in Alzheimer's disease and mild cognitive impairment." (PMID 39215401, 2024). "Evidence that Netrin-1 is involved in the pathogenesis of Alzheimer's disease has been found in cells, animals, and clinical experiments, indicating that Netrin-1 may be involved in the regulation of neuroplasticity." (PMID 35493300, 2022). "Thus, the molecular mechanisms in relation with the synaptic function of netrin-1 presents a new therapeutic target for neuropathology related to memory dysfunction including Alzheimer’s disease." (PMID 34884789, 2021). "Netrin signaling is similarly implicated in synaptogenesis, synaptic plasticity, Alzheimer's disease, schizophrenia, and brain tumor cell biology, suggesting that the significance of netrin-1 signaling via Cdc42 likely extends beyond roles directing chemotropic axon guidance." (PMID 27482713, 2016).
melanoma (14 papers, 2014 to 2025). A malignant, usually aggressive tumor composed of atypical, neoplastic melanocytes. "Netrin-1 encoded by NTN1 promotes the melanoma development coupled with its receptor DCC, which, in contrast, functioned as a tumor suppressor in intestinal cancer and lung metastasis by triggering cancer cell death." (PMID 37404751, 2023). "To further substantiate the effect of Netrin-1 on enhancing the migration of aggressive melanoma cells, we also probed the cell lysates from the rhNetrin-1-treated C8161 and Sk-Mel-28 for the pro-migratory/pro-metastatic molecule N-cadherin." (PMID 36361539, 2022). "To this end, we performed a migration assay with the Neogenin receptor expressing C8161 and Sk-Mel28 aggressive melanoma cells that were incubated in the presence of the Netrin-1-expressing SH-SY5Y cells or poor-Netrin-1-expressing HEKn human keratinocytes." (PMID 36361539, 2022). "Western blot analysis was used to determine baseline expression of Netrin-1 and Neogenin in the melanoma cell lines C8161, Sk-Mel28, UACC1273, and WM1552C." (PMID 36361539, 2022). "Postnatal expression of Netrin-1 is detected in brain, colon, liver, and kidney, which are common sites of cancer metastasis, including melanoma." (PMID 36361539, 2022). "Overall, our results support the role of Netrin-1/Neogenin interaction during the migration of melanoma cells towards Netrin-1 and that ERK1/2 signaling and N-cadherin expression are potentially involved in this migratory activity." (PMID 36361539, 2022). "Complementary to these results, treatment of C8161 and Sk-Mel28 aggressive melanoma cells with different concentrations of function-blocking anti-Neogenin antibody significantly reduced the migration of these cells towards the Netrin-1-expressing cells." (PMID 36361539, 2022). "Cell migration experiments show increased migration of Neogenin-expressing aggressive melanoma cells towards exogenous, soluble recombinant human Netrin-1 and towards a Netrin-1-expressing cell line." (PMID 36361539, 2022). "Since there is a scarcity of information regarding Netrin-1/Neogenin interaction in melanoma, the aim of this study is to determine if Neogenin receptor expression in melanoma cells can facilitate migration towards Netrin-1." (PMID 36361539, 2022). "Here, we show that Netrin-1/Neogenin interaction in aggressive melanoma cells leads to ERK1/2 activation and increased expression of N-cadherin." (PMID 36361539, 2022). "In our samples we detected nuclear netrin-1 in all different brain metastasis subentities with highest frequencies in melanomas and carcinomas NOS." (PMID 24647424, 2014). "By the comprehensive analysis of tumor–immune system interactions, we found that the difference in UNC5B expression was significant in urothelial carcinoma and melanoma immunotherapy, and the difference in NTN1 expression was also significant in melanoma immunotherapy." (PMID 41407823, 2025). "Netrin-1 inhibition in solid tumor xenograft models of melanoma have been shown to be effective in combination with chemotherapy, but its effects on a dormant scenario are unknown." (PMID 39023520, 2024). "Secondly, since Neogenin receptor plays a role in attracting cells towards Netrin-1, this suggests that Neogenin-receptor-positive melanoma cells could have a migratory advantage towards Netrin-1-expressing tissues during metastatic spread." (PMID 36361539, 2022). "WB results show variable expression of Netrin-1 in the different melanoma cell lines." (PMID 36361539, 2022). "Our data suggest that Neogenin receptors could play an important role during the metastatic spread of melanoma towards Netrin-1-expressing tissues such as the brain." (PMID 36361539, 2022).
melanoma (continued). "We conducted additional experiments to assess whether Neogenin receptor expressing melanoma cells are attracted towards a cellular source of Netrin-1." (PMID 36361539, 2022). "Moreover, treatment with anti-Neogenin blocking antibody caused decreased migration towards Netrin-1-expressing cells and reduced ERK1/2 activity in Neogenin-expressing aggressive melanoma cells." (PMID 36361539, 2022). "Here, we investigate whether the Netrin-1-attractive receptor Neogenin can affect migration of melanoma cells towards a Netrin-1 source." (PMID 36361539, 2022). "In summary, the results from our study provide the scientific rationale for exploring novel therapeutic approaches in targeting neuronal guidance factor/receptor interactions, such as Netrin-1/Neogenin, as a means to reduce disease progression and improve patient survival in melanoma." (PMID 36361539, 2022). "To elucidate the molecular mechanism through which the interaction of Netrin-1 and Neogenin receptors regulates migration, we performed WB analysis on the Neogenin receptor expressing aggressive melanoma cells C8161 and Sk-Mel28 treated with exogenous, soluble rhNetrin-1 and probed for pERK1/2." (PMID 36361539, 2022). "Reports of Netrin-1 and Neogenin in migratory and invasive processes of other neoplasias have also revealed complex downstream signaling activation, further confounding our understanding of the precise role of these molecules in melanoma progression." (PMID 36361539, 2022). "Since Alzheimer’s patients appear to have reduced melanoma incidence, the low Netrin-1 expression and high amyloid beta levels produced in Alzheimer’s brains could represent a possible protective factor against melanoma." (PMID 36361539, 2022). "In our study, we initially assessed Netrin-1 expression in melanoma cell lines." (PMID 36361539, 2022). "Interference with NTN-1 expression can reduce cancer cell death and promote melanoma progression." (PMID 35095412, 2021). "NTN-1 expression was elevated in melanoma compared with benign melanocytic lesions." (PMID 35095412, 2021). "Thus, understanding the dynamics between Netrin-1 and its receptors could explain the attraction of melanoma towards these Netrin-1-expressing tissues." (PMID 36361539, 2022). "We confirm that Netrin-1 can be detected by WB analysis in melanoma; however, we could not find significant differences in Netrin-1 expression between the aggressive and poorly aggressive melanoma cells studied." (PMID 36361539, 2022). "NTN1 knockdown induced increased expression of UNC5B and significantly weakened cell migration and invasion abilities in melanoma." (PMID 38546656, 2024). "In contrast, another report described expression of both Netrin-1 and DCC in melanoma, which appeared to play a role in survival and progression of melanoma." (PMID 36361539, 2022). "For instance, one study showed that melanoma cells do not express Netrin-1 or DCC but express UNC5 receptors, which trigger endothelial cell repulsion." (PMID 36361539, 2022). "Few studies have shown expression of these molecules in melanoma; however, it is not clear from these reports what precise role Netrin-1 and its receptors play during melanoma progression." (PMID 36361539, 2022). "In contrast, the relatively higher levels of Netrin-1 in brains of non-Alzheimer’s patients could facilitate the formation of metastatic melanoma lesions by attracting, as suggested by our data, Neogenin-receptor-expressing aggressive melanoma cells." (PMID 36361539, 2022). "However, netrin-1 and its receptor DCC also control the progression of melanoma, indicating that the therapeutic targeting of this signaling axis may be a viable method for melanoma treatment." (PMID 36499024, 2022).